SMURF1 (SMAD specific E3 ubiquitin protein ligase 1)
Diseases named in the same sentence as SMURF1 in open-access papers (continued):
Sharing a sentence is not in itself a finding about the gene and the disease.
prostate carcinoma (11 papers, 2018 to 2025). A carcinoma that arises from epithelial cells of the prostate gland. "Researchers have discovered that lncRNA SNHG3 is associated with miR-577/SMURF1 in prostate cancer and miR-139-5p/TOP2A in renal cell carcinoma." (PMID 36497046, 2022). "Recently, it has been reported that knocking out SMURF1 can reduce tumorigenesis in gastric cancer, prostate cancer, and ovarian cancer." (PMID 40342823, 2025). "Knocking out SMURF1 can reduce the occurrence of tumors in gastric cancer, prostate cancer, and ovarian cancer." (PMID 40342823, 2025). "On the whole, SNHG3 endogenously sponged miR‐577 to elevate SMURF1 expression, thus facilitating malignant phenotype of prostate cancer." (PMID 32248648, 2020). "It is for the first time that the ceRNA axis of SNHG3/miR‐577/SMURF1 was uncovered in prostate cancer cells." (PMID 32248648, 2020). "SMURF1 was aberrantly highly expressed in prostate cancer cells (*P < .05, **P < .01)." (PMID 32248648, 2020). "In this study, the functional role of SMURF1 in prostate cancer was unveiled." (PMID 32248648, 2020). "SNHG3/miR‐577/SMURF1 axis was found in prostate cancer cells." (PMID 32248648, 2020). "In conclusion, SNHG3/miR‐577/SMURF1 axis was found in prostate cancer cells." (PMID 32248648, 2020). "We innovatively uncovered the oncogenic role of SNHG3 and SMURF1 in prostate cancer, which might provide a new insight into identifying the biomarkers for prostate cancer." (PMID 32248648, 2020). "In addition, the authors demonstrated that expression of Smurf1 in prostate cancer cells is regulated through the androgen receptor (AR) signaling, which is critical for prostate cancer growth and survival." (PMID 30116722, 2018). "Also, SNHG3 targets miR-577 to up-regulate SMURF1 and heighten the development of prostate cancer." (PMID 35475457, 2022). "SNHG3/miR‐577/SMURF1 axis could modulate the progression of prostate cancer cells." (PMID 32248648, 2020). "In conclusion, SNHG3/miR‐577/SMURF1 axis could modulate the progression of prostate cancer cells." (PMID 32248648, 2020). "Therefore, SMURF1 expression was detected in prostate cancer cells via qRT‐PCR assay." (PMID 32248648, 2020). "For instance, Smurf1 accelerates PTEN ubiquitination and thus mediates prostate cancer and glioblastoma progression through the mTOR signaling." (PMID 35233069, 2022). "In prostate cancer, IMP3 is overexpressed, and it accelerates the cancer’s progression by increasing SMURF1-mediated PTEN ubiquitination, which in turn activates PI3K/AKT/mTOR signaling." (PMID 35366242, 2022). "All the results above explained that SNHG3 accelerated prostate cancer progression by sponging miR‐577 to up‐regulate SMURF1 expression, suggesting that SNHG3 may act as a biomarker for prostate cancer patients." (PMID 32248648, 2020).
pancreatic cancer (10 papers, 2011 to 2025). "Smurf1 amplification was found in primary human pancreatic cancers, and overexpression of Smurf1 leads to loss of contact inhibition of NIH-3T3 mouse embryo fibroblast cells." (PMID 31248165, 2019). "Additional studies should clarify the key SMURF1 substrates linked to invasiveness and anchorage-independent growth in pancreatic cancers with 7q22 amplification." (PMID 21887346, 2011). "Compared with the control group, the expression of SMURF1 in pancreatic cancer cells treated with Smurf1-in-A01 decreased (P<0.05)." (PMID 40342823, 2025). "In vitro experiments show that SMURF1 plays an important role in the proliferation and migration of pancreatic cancer cells." (PMID 40342823, 2025). "Patients with pancreatic cancer were divided into high and low expression groups based on the median expression levels of SMURF1 and SMURF2." (PMID 40342823, 2025). "In conclusion, our results show that inhibition of SMURF1 can inhibit the proliferation and migration of pancreatic cancer cells, and Smurf1-IN-A01 is a promising candidate drug for the treatment of pancreatic cancer." (PMID 40342823, 2025). "In vitro assays including CCK-8, EdU, colony formation, and wound-healing were employed to elucidate the function of SMURF1 in the proliferation and migration of pancreatic cancer cells." (PMID 40342823, 2025). "The effect of Smurf1-IN-A01 on the colony forming ability of PANC-1 and CFPAC-1 cells was evaluated using a colony formation assay to observe the long-term inhibitory effect of SMURF1 inhibition on the proliferation of pancreatic cancer cells." (PMID 40342823, 2025). "Five pancreatic cancer tissue samples confirmed by pathology were used to detect the difference in the expression of SMURF1 between pancreatic cancer tissue and paracancerous tissue." (PMID 40342823, 2025). "The findings suggest that inhibition of SMURF1 considerably reduced the migration capability of pancreatic cancer cells." (PMID 40342823, 2025). "Our results indicate that Smurf1-IN-A01 is an effective inhibitor of proliferation and migration of pancreatic cancer cells." (PMID 40342823, 2025). "High expression of SMURF1 showed a significant positive correlation with T staging, histological and pathological grades, as well as clinical treatment outcomes of pancreatic cancer (P<0.050)." (PMID 40342823, 2025). "The results showed that the expression of SMURF1 in some tissues of pancreatic cancer patients was higher than that in adjacent tissues." (PMID 40342823, 2025). "The data demonstrate that SMURF1 inhibition significantly impeded the colony forming ability of pancreatic cancer cells." (PMID 40342823, 2025). "Inhibition of SMURF1 expression suppressed the proliferation and migration of pancreatic cancer cells." (PMID 40342823, 2025). "Together, these findings identify SMURF1 as an amplified oncogene driving multiple tumorigenic phenotypes in pancreatic cancer, and provide a new druggable target for molecularly directed therapy." (PMID 21887346, 2011). "To summarize, by genomic profiling and functional analysis we identified SMURF1 as an amplified oncogene driving cell invasiveness in pancreatic cancer." (PMID 21887346, 2011). "SMURF1 amplification was confirmed in primary human pancreatic cancers by fluorescence in situ hybridization (FISH), where 4 of 95 cases (4.2%) exhibited amplification." (PMID 21887346, 2011). "All these activities should serve to antagonize TGFβ signaling, and together provide a strong rationale for SMURF1 amplification/overexpression in pancreatic cancer." (PMID 21887346, 2011). "Our findings identify SMURF1 as a possible new target for molecularly-directed therapy against the devastating disease of pancreatic cancer." (PMID 21887346, 2011). "To evaluate SMURF1 amplification in primary pancreatic tumors, we also carried out FISH on a tissue microarray containing 105 pancreatic cancer cases." (PMID 21887346, 2011).
pancreatic cancer (continued). "We speculate that inhibition of SMURF1 may inhibit the growth of pancreatic cancer cells by affecting cell cycle." (PMID 40342823, 2025). "The CCK-8 kit assay was used to evaluate the effect of Smurf1-IN-A01 in pancreatic cancer cells." (PMID 40342823, 2025). "We speculate that SMURF1 may promote apoptosis of pancreatic cancer cells and affect cell cycle progression by inhibiting the ubiquitin process of cells, thus inhibiting cell proliferation and migration." (PMID 40342823, 2025). "Extensive database analyses suggest that high SMURF1 expression may be a poor prognostic indicator for pancreatic cancer and a possible target for the treatment of pancreatic cancer." (PMID 40342823, 2025). "High expression of SMURF1 could potentially be a therapeutic target and a poor prognostic indicator in pancreatic cancer." (PMID 40342823, 2025). "SMURF1 was found to promote tumor invasion in pancreatic cancer." (PMID 35637952, 2022). "In pancreatic cancer, SMURF1 amplification promotes tumor invasiveness, suggesting that SMURF1 might be used as an indicator of progression and/or prognosis for some cancers including those of the head and neck." (PMID 25471937, 2014). "SMURF1 may represent a potential target for the treatment of pancreatic cancer." (PMID 40342823, 2025). "Indicating that Smurf1-IN-A01 might be a potential SMURF1 targeted drug for pancreatic cancer." (PMID 40342823, 2025). "Additionally, their expression was found to correlate with the clinical stage of pancreatic cancer, so it is postulated that increased expression of SMURF1 and SMURF2 may have prognostic value in identifying patients with a poor outcome." (PMID 40342823, 2025). "This dataset was utilized in the study to analyze the expression of SMURF1 and SMURF2 and their correlation with pancreatic cancer staging and patient survival." (PMID 40342823, 2025). "Co-expression analysis confirmed that SMURF1 and SMURF2 were highly correlated and co-regulated in pancreatic cancer." (PMID 40342823, 2025). "Analysis and comparison of OS, DSS and PFI revealed that SMURF1 and SMURF2 were expressed at higher levels in deceased pancreatic cancer patients compared to living patients." (PMID 40342823, 2025). "CBX3 ablation simply upregulated the expression of SMURF2 but not SMURF1 in pancreatic cancer cells." (PMID 35637952, 2022). "Because SMURF1 has been shown to inhibit mesenchymal stem cell proliferation and differentiation and to promote invasiveness and CSC properties in pancreatic cancer, we chose to validate its expression at the protein level and determine if BMP signaling was inhibited in the sphere cells." (PMID 25471937, 2014). "SMURF1 is a known inhibitor of TGFβ signaling (by promoting degradation of its receptor TGFβRI, and signaling mediator SMAD4), a pathway frequently disrupted in pancreatic cancer." (PMID 21887346, 2011). "By RNA interference (RNAi), knockdown of SMURF1 in a human pancreatic cancer line with focal amplification (AsPC-1) did not alter cell growth, but led to reduced cell invasion and anchorage-independent growth." (PMID 21887346, 2011). "Furthermore, SMURF2 but not SMURF1 was downregulated in CBX3-overexpressed pancreatic cancer cells." (PMID 35637952, 2022). "In this study, we demonstrated that CBX3 downregulated SMURF2 but not SMURF1, consistent with the biological function of CBX3 in pancreatic cancer." (PMID 35637952, 2022).
ovarian carcinoma (9 papers, 2019 to 2025). A malignant neoplasm originating from the surface ovarian epithelium. "Similarly, SMURF1 has been found to be increased in ovarian cancer patients and be associated with cell migration and invasion in ovarian cancer." (PMID 31004081, 2019). "Down‐regulation of SMURF1 inhibits ovarian cancer invasion and EMT (Epithelial‐mesenchymal transition) process through modulation on DAB2IP/AKT/Skp2 axis." (PMID 32248648, 2020). "The third is the Nedd4-like E3 ligase Smurf1 (SMAD-specific E3 ubiquitin-ligase 1) in ovarian cancer." (PMID 33096593, 2020). "Increased SMURF1 expression was observed in ovarian cancer cell lines compared with that in IOSE80 cells, with the lowest expression detected in SKOV3 cells." (PMID 31004081, 2019). "In this study, we report that ARHGAP26 is downregulated, whereas β-catenin and SMURF1 are upregulated in ovarian cancer patients." (PMID 31004081, 2019). "We analyzed the mRNA expression levels of β-catenin and SMURF1 in ovarian cancer tissues and performed a Pearson’s correlation analysis between ARHGAP26 and β-catenin or SMURF1 and β-catenin." (PMID 31004081, 2019). "ARHGAP26 mRNA expression was negatively correlated with the mRNA expression of β-catenin in ovarian cancer tissues, whereas SMURF1 mRNA expression was positively correlated with the mRNA expression of β-catenin in ovarian cancer tissues." (PMID 31004081, 2019). "Interestingly, upregulation of ARHGAP26 in SKOV3 ovarian carcinoma cells was shown to effectively inhibit the migration and invasion of tumor cells due to the upregulation of smad ubiquitination regulatory factor 1 (SMURF1)." (PMID 34716859, 2022). "Moreover, an increased level of SMURF1, which was detected in 80 ovarian serous cystadenocarcinoma samples, was accompanied by a shorter overall survival of patients with ovarian cancer." (PMID 32443784, 2020). "SMURF1-mediated ubiquitination of ARHGAP26 may promote ovarian cancer cell invasion and migration through the β-catenin signaling pathway." (PMID 31004081, 2019). "Moreover, SMURF1 mRNA expression was positively correlated with β-catenin mRNA expression in ovarian cancer tissues." (PMID 31004081, 2019). "Our results provided evidence, suggesting that ARHGAP26 inhibits ovarian cancer cell invasion and migration in vivo and in vitro, and SMURF1-mediated ARHGAP26 ubiquitination may promote ovarian cancer cell invasion and migration via the β-catenin signaling pathway." (PMID 31004081, 2019). "ARHGAP26 overexpression inhibited SMURF1-mediated cell migration, invasion, and β-catenin signaling in ovarian cancer, thereby suggesting that SMURF1-mediated ARHGAP26 ubiquitination may promote ovarian cancer cell invasion and migration via the β-catenin signaling pathway." (PMID 31004081, 2019). "Furthermore, SMURF1 expression levels in ovarian cancer cell lines were also measured." (PMID 31004081, 2019). "SMURF1‐mediated ubiquitination of ARHGAP26 promotes cell migration and invasion in ovarian cancer cells." (PMID 32248648, 2020). "The depletion of Smurf1 increases DAB21P expression and results in the impairment of the EMT process as well as cell proliferation and invasion in ovarian cancer cells." (PMID 33114139, 2020). "The correlation of SMURF1 overexpression and RhoA/ROCK signaling pathways promoting metastasis was observed in ovarian cancer cell lines (OVCAR3)." (PMID 32443784, 2020). "A recent report identified the role of Smurf1 in promoting cell migration and invasion capacities through the ubiquitination of DAB21P in ovarian cancer cells." (PMID 33114139, 2020). "Smurf1 also leads to the invasion and metastasis by the interaction and ubiquitination of Rho GTPase-activating protein 26 (ARHGAP26) in ovarian cancer cells." (PMID 33114139, 2020). "SMURF1 upregulation promoted ubiquitination of ARHGAP26 and induced ovarian cancer cell migration and invasion, which were inhibited by ARHGAP26 upregulation." (PMID 31004081, 2019).
ovarian carcinoma (continued). "Thus, researchers believe that SMURF1-dependent regulation of ARHGAP26 ubiquitination promotes the invasion and migration of ovarian cancer cells through the β-catenin pathway." (PMID 34716859, 2022). "The results demonstrated upregulated mRNA expression of β-catenin and SMURF1 in ovarian cancer tissues compared with corresponding adjacent noncancerous ovarian tissues from our independent hospital cohort." (PMID 31004081, 2019). "Overall, SMURF1-mediated ubiquitination of ARHGAP26 may promote invasion and migration of ovarian cancer cells via the β-catenin pathway." (PMID 31004081, 2019). "Nevertheless, the cellular function of SMURF1 and its role in regulation of ARHGAP26 in ovarian cancer remain largely unknown." (PMID 31004081, 2019). "Notably, deletion of SMURF1 in ovarian cancer cells increased DAB2IP levels and reduced proliferation, invasion and EMT; depletion of DAB2IP restored proliferation and EMT in SMURF1-knockout cells, suggesting that SMURF1 is required to maintain low levels of DAB2IP in ovarian cancer." (PMID 38902547, 2024). "They revealed that the absence of Smurf1 represses cell proliferation, invasive capability, and EMT process in ovarian cancer through DAB2IP/AKT/Skp2 signaling loops." (PMID 35654587, 2022).
colon cancer (7 papers, 2019 to 2025). "Collectively, this study validates SMURF1 as an attractive target for colon cancer, particularly in cases harboring KRAS mutations." (PMID 39331402, 2025). "Consistently, the analysis of the TCGA database revealed that SMURF1 is significantly upregulated in colon cancer tissues harboring KRAS mutations, and the high SMURF1 expression is positively associated with poor survival of colon cancer patients." (PMID 39331402, 2025). "The immunohistochemistry-based analysis of colon cancer tissues showed that elevated SMURF1 levels correlated with poor survival of patients with KRAS mutation." (PMID 39331402, 2025). "Recently, IRAK2 has also been described as a potential tumor suppressor in colon cancer that counterbalances oncogenic Smurf1 by phosphorylation of its threonine residues and promoting its self-degradation by ubiquitylation." (PMID 32841292, 2020). "As a tumor suppressor, Casein kinase-2 interacting protein-1 (CKIP-1) represses Smurf1 synthesis and is responsible for autoubiquitination and degradation of Smurf1 in colon cancer cells." (PMID 33718111, 2020). "The present study was the first to reveal that miR‐125a can decrease the Smurf1 mRNA and protein expression levels in colon cancer cells by directly targeting the 3′‐UTR of Smurf1, which suggests that Smurf1 is a potent target of miR‐125a for CRC prevention and treatment." (PMID 31141316, 2019). "We verified that Smurf1 is a downstream target gene of miR‐125a and is involved in miR‐125a‐mediated regulation of CT26 cell (colon cancer cell) proliferation and migration." (PMID 31141316, 2019). "Finally, a positive correlation among the SMURF1 level, PDK1 neddylation, and AKT phosphorylation in colon cancer tissues was found." (PMID 39331402, 2025). "Moreover, aberrantly expressed SMURF1 in colon cancer samples inversely correlated with the expression of CKIP-1, which repressed the SMURF1 synthesis and promoted SMURF1 autoubiquitination and degradation, thereby suppressing colon cancer cell growth and migration." (PMID 36831013, 2023).
gastric cancer (7 papers, 2018 to 2025). A primary or metastatic malignant neoplasm involving the stomach. "Expression of SMURF1 was negatively associated with the survival of patients with gastric cancer and clear cell renal cell carcinoma (ccRCC)." (PMID 40342823, 2025). "The expression level of SMURF1 is negatively correlated with the survival rate in gastric cancer and renal clear cell carcinoma." (PMID 40342823, 2025). "Genomic hybridization analyses indicates that SMURF1 is a potential oncogenic factor in gastric cancer." (PMID 40342823, 2025). "Genomic hybridization suggests that SMURF1 is a determining factor for oncogenesis in pancreatic cancer and gastric cancer." (PMID 33418880, 2021). "These new reports propose Smurf1 as a potential therapeutic drug target in ovarian and gastric cancer, respectively." (PMID 33114139, 2020). "SMURF1 levels are inversely corelated with survival rate in patients with gastric cancer (GC), colorectal cancer, and ccRCC." (PMID 33418880, 2021). "miR-1254 targets Smurf1 to frustrate PI3K/AKT pathway activation, thereby suppressing gastric cancer proliferation, metastasis, and EMT." (PMID 34983307, 2022). "Smurf1 is also overexpressed in human gastric cancer (GC) tissues." (PMID 30116722, 2018). "Recent studies have shown a negative correlation between Smurf1 expression levels and survival rates in gastric cancer and renal clear cells." (PMID 40342823, 2025). "Moreover, Smurf1 was reported to be negatively regulated by miR-1254, reducing EMT and PI3K/AKT signaling pathway in gastric cancer, further supporting its involvement in EMT." (PMID 33114139, 2020).